CD4 (CD4 molecule)
Diseases named in the same sentence as CD4 in open-access papers (continued):
Sharing a sentence is not in itself a finding about the gene and the disease.
tumor (continued). "CD4 + FOXP3 + Treg cells also demonstrated extensive communication with other cells in LCC, but there was relatively limited interaction between immune cells and tumor cells." (PMID 39267963, 2024). "However, the percentages of CD4 and CD8 T cells among total CD45 + cells in tumor were comparable between Gpr84CKO and littermate control (Supplemental 4G, H)." (PMID 38349405, 2024). "STC1 may influence the infiltration and activity of CD8+ T cells and CD4+ T cells by modulating pro-inflammatory or immunosuppressive factors, such as TGF-β, within the tumor microenvironment." (PMID 39201771, 2024). "On the other hand, CD4 + and CD8 + T cells trigger tumour escape by expressing immune checkpoint molecules (PD-1, LAG-3, CTLA-4, TIM-3) that bind to their related ligands on DCs and/or tumours, thereby stopping an immune reaction." (PMID 39720956, 2024). "This peptide-based cancer vaccine was evaluated in a HER2+ breast cancer mouse model, resulting in a promising immune response of CD8+ and CD4+, a significant cytokine secretion of IL-4 and IFN-γ, and a notable reduction in tumor size and increase of survival time." (PMID 37587290, 2024). "Quantification of the identified cell populations revealed no increase in proliferating CD8+ or CD4+ Tconvs in LNs upon TC-1 tumor outgrowth." (PMID 38349740, 2024). "Despite constituting only approximately 6% of the total tumor cells, this population exhibited upregulation of MHC-II genes and actively interacted with immune cells, such as CD4+ T cells, prevalent in TNBC patients who have better survival outcomes, i.e., the nonTD patient group." (PMID 39664386, 2024). "Therefore, we measured the distribution of CD4+ T, CD8+ T, and activated CD8+ T cells (CD69+CD8+) in peripheral blood, sentinel lymph nodes, and tumor-bedding sites." (PMID 38279092, 2024). "PD-L1 is a key player in tumor immune suppression, and studies have shown that PD-L1 signaling including PD-1/PD-L1 and CD80/PD-L1 is crucial for T cell migration, modulating transendothelial movements of Tregs and CD4 effector T cells." (PMID 38529320, 2024). "However, on the other hand, granzyme B is also capable of inhibiting the proliferation of CD4+ and CD8+ T cells, thereby favoring tumor growth." (PMID 38927922, 2024). "Furthermore, CD4+ T cells also help CD8+ T cells maintain and infiltrate at a tumor site by rendering the tumor environment permissive." (PMID 38355548, 2024). "Additionally, because of their plasticity, CD4+ T cells can convert into Treg cells secreting IL-10 and TGF-β, suppressing immune responses and aiding in tumor immune escape." (PMID 38292868, 2024). "The cell–cell interaction analysis results show how cancer epithelial cells interact with the main players in the tumor microenvironment, including fibroblasts, macrophages, endothelial cells, CD8+ T cells, CD4+ T cells, and tumor cells themselves (cancer epithelial cells)." (PMID 38539508, 2024). "Through the elevated levels of CD4+ T cells previously found in BRAF-mutant tumor samples, the BRAF-mutant TME can promote anti-tumor activity through the direct or indirect targeting of tumor cells by CD4+ T cells, which also supports the cytotoxic effects of CD8 + T cells on tumor cells." (PMID 39336897, 2024). "Notably, compared with tumors with high SUVmax by 68Ga-FAPI PET imaging, 68Ga-FAPI PET/CT–negative tumors showed low FAP-α protein expression and contained a significantly higher number of tumor-infiltrating CD8+ T cells and CD4+ T cells." (PMID 38175716, 2024). "Interestingly, the combined treatment based on mCelyvir and intratumoural injections of ICOVIR5 was found to act by inhibition of neoplastic growth and induction of CD4+ and CD8+ T cell recruitment to the tumour microenvironment." (PMID 39120301, 2024). "Another limitation of this model is that it does not account for effects of CD4+ T cells on tumor cell killing." (PMID 40809127, 2024).
tumor (continued). "To test this hypothesis, we performed immunohistochemistry (IHC) to quantify the density of CD4+ T cells, CD8+ T cells, CD20+ B cells and CD45RO+ cells on 242 LARC tumor tissues from the NT cohort." (PMID 38431733, 2024). "In the PI3K/mTORi‐treated tumours clonal T cells were almost exclusively confined to the CD8+ Tex‐cell population, while in the PI3K/mTORi+PD‐1i‐treated tumours, clonally expanded T cells primarily belonged to the CD8+ Teff‐ and CD4+ Th1‐cell population." (PMID 38711203, 2024). "For a comprehensive view of the tumor-infiltrating T cell landscape, the markers CD3, CD8, CD4, Programmed Cell Death Protein (PD)-1, granzyme B (GrzB) and Forkhead-Box-Protein P3 (FoxP3) were employed in addition to 4′,6-Diamidin-2-phenylindol (DAPI) nuclear staining." (PMID 38631706, 2024). "CD4 + and CD8 + T cells play a major role in the anti-tumor immune response in humans." (PMID 38926205, 2024). "T cells also play an important role in tumor initiation and progression, as CD4 + T cells may inhibit tumor formation, while CD8 + T cells may promote tumor cell survival." (PMID 38789691, 2024). "On the contrary, tumor-infiltrating HBV-specific CD4+ T cells were significantly elevated compared with all control groups (non-HBV HCC, CHB, and HC), with Tregs being the predominant CD4+ T-cell subset." (PMID 38793588, 2024). "Based on our current results and previous literature, it is likely that a major part of IL-17 produced in the tumour microenvironment is provided by CD4+ Th17 cells, rather than γδ17 cells." (PMID 38953978, 2024). "Conversely, stromal regions were associated with a substantial abundance of lineage-defining immune markers (CD3, CD8, CD4, CD20, CD14, CD11C), confirming a complex, but tumor-excluded immune environment prior to treatment in most patients regardless of response status." (PMID 39638782, 2024). "This indicates a possible interaction between macrophages and both T cell subsets (CD4+ and CD8+), as well as other macrophages (CD163+), suggesting that macrophages in the tumor center might play a central role in coordinating the immune response." (PMID 39338178, 2024). "Moreover, Delta-24-RGDOX led to higher levels of CD4+ and CD8+ T cell infiltration and activity in the tumour environment than Delta-24-RGD." (PMID 38732225, 2024). "Interestingly, although we observed immune‐active tumor‐reactive CD8+ T cells within the HRD TIME, immune‐suppressive CD4+ Tregs were also enriched." (PMID 39136172, 2024). "To validate the EPIC-derived conclusions regarding immune cell involvement in tumor microenvironments, we employed CIBERSORT to assess the infiltration abundances of plasma cells, activated CD4+ T cells, CD8+ T cells, M1 macrophages, and activated NK cells within GSE32894 tumor samples." (PMID 38696324, 2024). "The cytotoxicity of CD4+ T cells enables them to directly target tumor cells independent of CD8+ T cell assistance." (PMID 38426090, 2024). "Additionally, the TLS density was significantly positively correlated with CD4+ T cells, CD8+ T cells, CD20+ B cells, CD45RO+ memory T cells and NCR1+ NK cells and negatively correlated with CD15+ TANs in the tumor centre." (PMID 38322490, 2024). "Notably, the TCR effectively redirected both CD4+ and CD8+ T cells to specifically recognize tumor cells and induced multiple cytokine secretion along with durable antitumor activity and outstanding safety profiles." (PMID 38480731, 2024). "Furthermore, the study identified interactions between disulfidoptosis-mediated CD4+ T cells, CD8+ T cells, Treg cells, B cells, and tumor cells were identified, each demonstrating distinct functional characteristics." (PMID 38292868, 2024). "Tumor microenvironment (TME) analysis results indicated the presence of immune infiltration in DN GSE30529, primarily memory B cells (MBCs), CD8+ T cells, γδ T cells, resting memory CD4+ T cells, and M0 macrophages." (PMID 37143982, 2023).
tumor (continued). "Activated CD4 + memory cells, rather than resting cells, play important role in anti-tumor immunity." (PMID 36930369, 2023). "For example, CD4+ helper T cells are responsible for providing regulatory cytokines required to activate CD8+ T cell soluble T lymphocytes, which are considered to be important effector cells for killing tumor cells." (PMID 37792639, 2023). "Other tumor-restricted antigens targeted with CAR-T cells include CCR4, CD4, and CD30." (PMID 37711206, 2023). "In addition, necroptosis also increases the infiltration of T cells, including CD4+ and CD8+ T cells, into the tumor microenvironment." (PMID 37373523, 2023). "Short-course RT and long-course CRT have been shown to increase the number of T-lymphocytes in the tumor microenvironment of locally advanced rectal carcinomas, although no significant alterations were noted in the CD4+ and CD8+ lymphocyte counts." (PMID 37232754, 2023). "Furthermore, we selected the prime-boost regimen with the lowest dose of vaccine (3 μg) to profile the ratio of CD4 and CD8 T cells infiltrating the tumor." (PMID 37503351, 2023). "CD4+ TIL subpopulations also exhibited CD25+CD137+ and CD39+TIM-3+ phenotypes (data not shown), supporting the notion that CD4+ TREG cells accumulate in MC38 tumours given that these markers are highly and selectively expressed by this subset." (PMID 37153625, 2023). "We noticed that while TCR richness in non-tumor tissues was elevated, suppressive CD4+ T cells such as Treg, which are highly expressed in tumor compared with non-tumor tissues, changed less with tumor progression." (PMID 37313417, 2023). "Both ablation treatment arms containing liposomal preparations, RFA-lip-GM-CSF and RFA-BL, had increased CD11C+ and CD8+ and CD4+ lymphocytes infiltration in the synchronous non-ablated tumor at 7d compared to either RFA alone or sham treatment (p<0.05)." (PMID 37883367, 2023). "This could be reasonable that higher infiltration of CD4+ T and CD8+ T cells resulted in higher expression of IFN‐γ, which facilitates tumor ferroptosis and then patients' prognosis." (PMID 35855531, 2023). "Specifically, MHC-II expression on tumor cells was found to be predictive of response to anti-PD1, and it was hypothesized that they represented a subset of tumors capable of stimulating CD4 T-cells or CD8 T-cells." (PMID 37569757, 2023). "Additionally, protein kinase B (PKB) inhibitors promote lipid oxidation metabolism, fetch up CD4+ T cell markers, such as SRC, and ameliorate tumor-specific lymphocytes." (PMID 38328405, 2023). "MHC molecules in DCs are necessary for an efficient tumour antigen presentation, and exosomes can be used to achieve that goal: MHC class I molecules to induce cytotoxic CD8+ T cells, and MHC class II molecules to effectively activate CD4+ T cells." (PMID 37022605, 2023). "The synergetic roles of PX and biomimetic CS‐J@CM/6 nanoparticles drastically improved infiltration of antitumor immune cells (CD8+ T, CD4+ T, and TEM) in tumor, spleen, and lymph nodes, and decreased the immunosuppressive Treg cells in tumor, resulting in an excellent immunotherapy efficacy." (PMID 36698265, 2023). "Enrichment of T-cell markers (CD3, CD4), macrophage markers (CD68, CD168), immune checkpoints (CD27 and V-domain Ig suppressor of T-cell activation [VISTA]), CD44 and CD45 were seen in the stroma relative to the tumour." (PMID 37835491, 2023). "In this review, we also discussed the effects of innate immune cells on tumor cells since immuno-oncology drugs may exacerbate ACD possibly via the activation of CD8+ and/or CD4+ T cells and the inactivation of regulatory T cells and tolerogenic DCs." (PMID 37629154, 2023). "Second, we evaluated the Siglec15 and PD-L1 expression and T-cell markers such as CD4 and CD8 using TMA IHC and focused on information within SA, which may have ignored some other information regarding the tumor." (PMID 37859817, 2023).
tumor (continued). "Collectively, these data indicate that CD8+ T cell-restricted peptides originating from self-tumor antigens like hTERT and WT-1 activate not only self-reactive CD8+ T cells but also are likely to cross-activate CD4+ T cells, including Foxp3+ Treg cells with self-reactive TCRs." (PMID 37761976, 2023). "Besides, cDC2 presents tumor antigens to CD4+ Tn cells via the MHCII and activates the initial immune response of CD4+ Tn." (PMID 38018578, 2023). "Furthermore, we observed that CD4+ CTLs produce CXCL13 that potentially interacts with activated B cell populations, including DN B cells, through physical conjugation in tumor lesions." (PMID 38077321, 2023). "Consistent with the RNA-seq results was the finding that, in the MC38 tumor-bearing mice, CBPA treatment could increase CD4+ and CD8+ T-cell infiltration in the tumor tissue, which may have been caused by T-cell proliferation." (PMID 36835382, 2023). "Here, we show that the Kindlin-1-dependent regulation of IL-6 secretion controls the differentiation of CD4+ T cells into FoxP3+ Tregs and the ability of Tregs to suppress CD8+ T cell proliferation in vitro, while also regulating Treg numbers in the tumor microenvironment." (PMID 36883731, 2023). "We did not observe any association of CD4+ and CD8+ cell numbers in the tumor center or in the invasion front with OS." (PMID 36836239, 2023). "The therapeutic effect of immune checkpoint inhibitors on tumor is not solely attributable to CD8+ effector T cells but is also noticeably reliant on CD4+ helper T cells." (PMID 37329188, 2023). "Results showed an increased number of anti-tumoral immune cells such as CD8+ (with a reduced CD4+/CD8+ ratio), NK and DCs, and a reduced number of pro-tumoral immune cells such as Treg and MDSC, in tumor masses of SR59230A-, αPD-L1- and SR59203A + αPD-L1-treated mice compared to vehicle condition." (PMID 36854895, 2023). "CAF-S1, a subset of myofibroblast, recruits CD4+CD25+ T cells to create an immunosuppressive microenvironment via CXCL12 and expresses B7H3, CD73, and DPP4 to promote their differentiation into Tregs, thereby contributing to tumor growth." (PMID 37784082, 2023). "While levels of TReg cell infiltration exist in MBL tumours compared to noncancerous tissue, they are paired with lower counts of CD4+ T cells overall." (PMID 37232837, 2023). "Our data indicate that neither CD4+ T cells nor CD8+ T cells play an essential role in preventing the tumor development induced by MDV." (PMID 36992357, 2023). "In addition, tumor-infiltrating CD4+ and CD8+ T cells were significantly elevated in TLO+ tumor tissues, providing an antitumor immune microenvironment." (PMID 37529035, 2023). "Following CD4+ T cell stimulation, CD8+ cytotoxic lymphocytes (CTLs) activate the T cell mediated immune response, resulting in the killing of tumour cells, as a result of the interaction between TCR molecules and the MHC class I complex αβ dimer and β2 microglobulin (B2M)." (PMID 36980527, 2023). "We indeed observed that a low dose of Lipo-MP-LPS did not induce tumor infiltration by CD4+ T-cells, although it increased the levels of M1 macrophages in tumors and production of proinflammatory cytokines and chemokines." (PMID 37760603, 2023). "Since MALAT1 is expressed in various cell types, and affects the function of CD8+ and CD4+ T cells, it remains to be seen whether SELs or siRNAs that target MALAT1 are effective in inhibiting the growth of different tumor types." (PMID 37346034, 2023). "Besides evidence of CD4 and CD8 T-cell presence in tumor biopsies from patients 1, 2, and 10, also a relative abundance of Tregs and B-cells was noted." (PMID 36859619, 2023). "Spatial distances of CD4+ T cells–CD38+ T cells, CD4+ T cells–neutrophils and CD38+ T cells–neutrophils prolonged and they were replaced by CD163+ macrophages in PT along with tumour progression." (PMID 37491740, 2023).
tumor (continued). "The ratio of Treg cells was significantly decreased in tumour tissues of anti-CCL28-treated mice, but the ratios of CD8+ and CD4+ T cells were not changed by anti-CCL28 treatment in tumour tissues." (PMID 37380804, 2023). "In addition, we found that MS4A6A expression also correlated significantly with CD8+ and CD4+ T cells, suggesting the relevance of MS4A6A in tumor killing." (PMID 37578930, 2023). "Alternatively, patients with LM who are non-responders may have genetic polymorphisms that influence the secretion of interleukin-10, an inhibitory cytokine that slows the generation of CD4 and CD8 effector T cells, which are able to kill tumor cells." (PMID 36900337, 2023). "Therefore, higher numbers of CD4 + and CD8 + T cells indicate more lymphocyte infiltration into the tumor tissue, which lead to tumor regression." (PMID 37704828, 2023). "Subsequent studies investigating tumor fucosylation, total/fucosylated HLA-DRB1 and CD4+ T cells as biomarkers will need to factor for clinical variables including therapies received before anti-PD1 therapy and pre-existing medical conditions as well as time from biopsy to anti-PD1 treatment." (PMID 36690875, 2023). "In this study, we assessed the total TIL, CD4+TIL, and CD8+TIL levels in naïve and post‐chemotherapy tumor tissue specimens from the same patients and explored the prognostic value differences between naïve and post‐chemotherapy tumor tissue specimens." (PMID 36789099, 2023). "Thus, the negative correlation of risk score with activated CD4+ T cells and mast cells and the positive correlation with other immune cells, suggesting that the 6-characteristic genetic risk score model is closely related to the immune activation status in the tumor microenvironment." (PMID 38273850, 2023). "CD4+ T cells with upregulated cytotoxic features have been shown to mediate MHC class II-dependent elimination of virus-infected cells and tumor cells, suggesting that B cells may kill via cognate interactions with CD4cyt." (PMID 37161048, 2023). "Tumor cell metastasis and drug resistance are impacted by epithelial–mesenchymal transition (EMT), and naïve CD4+ T-cell recruitment might inhibit TI Tregs, restore immune tumor killing, and inhibit cancer growth and metastases." (PMID 37818090, 2023). "Indeed, the HRS proximal region, also called the neoplastic niche, is usually enriched in PD-1+CD4+ T cells, which interact with both PD-L1+ TAM and PD-L1+ tumor HRS cells." (PMID 37372147, 2023). "Furthermore, this PhoXCELL strategy allowed to simultaneously detect tumor antigen-specific CD8+ and CD4+ T cells from tumor-infiltrating lymphocytes and draining lymph nodes in preclinical mouse models." (PMID 37376918, 2023). "CD4+ and CD8+ lymphocytes, dendritic cells, eosinophils, macrophages, monocytes, and NK cells are immune system cells that depend on CC family chemokines for survival, as does tumor development." (PMID 36976996, 2023). "We evaluated the number of CD4+ and CD8 + TIL per mm2 tumor area in those animals that developed tumors (3 TOP2A vaccinated and 12 CpG control mice) and observed that TOP2A vaccination significantly increased CD4+ and CD8 + TIL over adjuvant controls (p < 0.01)." (PMID 37880313, 2023). "In contrast to the effects of adding CD8+ T cells alone, tumor growth was not blocked in untreated or TI treated mice, suggesting inhibitory cells (possibly MDSCs or CD4+ Tregs) were also present." (PMID 37700795, 2023). "Targeting Tregs using anti‐CTLA4 antibody combined with M1 oncolytic viruses induced tumor suppression and lymphocytotoxicity via decreasing Tregs and increasing the infiltration of CD45+ immune cells CD4+ or CD8+ T cells, releasing IFN‐γ, perforin, and granzyme." (PMID 36618103, 2023). "As a result, very weak NeoAg-specific CD8+ T-cell responses have been obtained from patients, in contrast to NeoAg-specific CD4+ T-cells which are not the main effectors of anti-tumor immune response." (PMID 36726965, 2023).